IAPP (islet amyloid polypeptide)
Diseases named in the same sentence as IAPP in open-access papers (continued):
Sharing a sentence is not in itself a finding about the gene and the disease.
type 2 diabetes (continued). "Although CHOP is not the only mediator for apoptosis of the β-cells, these results indicate the relationships between IAPP and ER stress and that IAPP may be one of the associated proteins of type 2 diabetes." (PMID 35205066, 2022). "Glucotoxicity, lipotoxicity, endoplasmatic reticulum (ER) stress, oxidative stress, islet amyloid polypeptide (IAPP), and inflammation and are responsible for the loss of pancreatic mass, leading to progressive β-cell failure of the pancreas in type 2 diabetes." (PMID 35054822, 2022). "For this reason, the opinion that IAPP is the main cause of type 2 diabetes is highly convincing." (PMID 33883656, 2021). "In addition, the aggregation of islet amyloid polypeptide (IAPP) and insulin is implicated in the pathogenesis of type 2 diabetes." (PMID 34578556, 2021). "These approaches have been shown to restrict the self-assembly of a range of model amyloid peptides, including those derived from Aβ [30,], tau (involved in Alzheimer's disease and other neurodegenerative disorders), β2m, and islet amyloid polypeptide (IAPP; associated with type II diabetes)." (PMID 33220582, 2021). "Work by the same group provided the first experimental evidence of an interaction between two IDPs whose aggregation is associated with diseases in different tissues, namely, islet amyloid polypeptide (IAPP), implicated in type 2 diabetes, and a fragment of tau, implicated in Alzheimer’s." (PMID 33791275, 2021). "Sulfation is already known to play a role in pancreatic islets, where in that glycolipid sulfatides are involved in normal insulin secretion and sulfation of heparin sulfate has been implicated in islet amyloid polypeptide aggregation in type 2 diabetes mellitus." (PMID 33581409, 2021). "The aggregation of the human islet amyloid polypeptide (IAPP) is associated with diabetes type II." (PMID 34790701, 2021). "In addition to Aβ peptide, an impact from the NP-PC complex on the fibrillation process of human islet amyloid polypeptide (IAPP), the fibrillation of which is a hallmark of type 2 diabetes, has also been reported." (PMID 32664362, 2020). "The human islet amyloid polypeptide (hIAPP), the major component of islet amyloid deposition, is one of the amyloidogenic peptides and has been associated with β cell loss and dysfunction in type 2 diabetes (T2D)." (PMID 31447682, 2019). "The hallmark of type II diabetes mellitus (in 95% of cases) is the loss of pancreatic β-cells, which is coincident with extracellular deposition of amyloid aggregates formed by a 37 amino acid peptide, IAPP." (PMID 28937634, 2017). "Human Amylin, or islet amyloid polypeptide (hIAPP), is a small hormone secreted by pancreatic β-cells that forms aggregates under insulin deficiency metabolic conditions, and it constitutes a pathological hallmark of type II diabetes mellitus." (PMID 27322259, 2016). "Several sources suggest a causal relation between IAPP and Type II Diabetes." (PMID 26221949, 2015). "However, over the last two decades, numerous studies have shown a prominent role of amyloid cofactors in IAPP fibrillogenesis associated with the etiology of type II diabetes." (PMID 26576436, 2015). "In type 2 diabetes, beta-cell dysfunction is thought to be due to several causes, one being the formation of toxic protein aggregates called islet amyloid, formed by accumulations of misfolded human islet amyloid polypeptide (hIAPP)." (PMID 25010593, 2014). "Furthermore, resveratrol seems to be able to interact with IAPP implicated in type II diabetes and to prevent fibril formation and cytotoxicity." (PMID 23242152, 2012). "Therefore, the accumulation of IAPP aggregates is closely linked to β-cell dysfunction and loss, contributing to the progression of type 2 diabetes by overwhelming the cells’ protein degradation systems, inducing oxidative stress, and ultimately triggering apoptosis." (PMID 41409210, 2025).
type 2 diabetes (continued). "Therefore, despite the proximity of aSyn and IAPP in β-cells and the detected capacity of preformed aSyn fibrils to seed IAPP in vitro, it is still an open question if an interaction between the two molecules is of pathogenic significance for type 2 diabetes." (PMID 36793785, 2023). "Numerous studies have demonstrated that people with type 2 diabetes mellitus (associated with IAPP peptide aggregation) show an increased incidence of Alzheimer’s disease (associated with Aβ aggregation), but the mechanism responsible for this correlation is presently unknown." (PMID 37762425, 2023). "The cytotoxic self-aggregation of β-amyloid (Aβ) peptide and islet amyloid polypeptide (IAPP) is implicated in the pathogenesis of Alzheimer’s disease (AD) and Type 2 diabetes (T2D), respectively." (PMID 35372522, 2022). "Amyloids formed by the short islet amyloid polypeptide (IAPP) in the pancreas is associated with type 2 diabetes (T2D)." (PMID 33244624, 2021). "A hallmark of T2DM is the occurrence of IAPP-derived amyloid aggregates in the pancreatic islets, which is associated with β-cell toxicity and inflammasome-mediated IL-1β production and inflammation, leading to the characteristic loss of β-cell mass in type 2 diabetes mellitus." (PMID 32131431, 2020). "Here, we explored the effects of the MDP-analog, humaninS14G (HNG), and the MDP, small humanin-like peptide 2 (SHLP2), on the misfolding of islet amyloid polypeptide (IAPP), a critical pathogenic step in type 2 diabetes mellitus (T2DM)." (PMID 28798389, 2017). "Thus, molecular imaging could help inform treatment strategies and prognostication (e.g. in patients with type 2 diabetes, the IAPP amyloid load may act as a surrogate for β-cell loss in the pancreatic islets -)." (PMID 23750281, 2013). "In addition, pancreatic amyloid composed of islet-associated polypeptide (IAPP) that is common in patients with type 2 diabetes and may have etiologic significance, has yet to be imaged using SAP or any other radiotracer." (PMID 23750281, 2013). "In type 2 diabetes, the aggregation of Islet Amyloid Polypeptide (IAPP), a process often nucleated via LLPS, contributes to pancreatic β-cell dysfunction." (PMID 41596484, 2026). "Type 2 Diabetes (T2D) is characterized by the toxic aggregation of human islet amyloid polypeptide (hIAPP or amylin) within pancreatic β-cells." (PMID 41898768, 2026). "The human islet amyloid polypeptide (hIAPP) aggregates into amyloid fibrils that contribute to β-cell failure in type 2 diabetes." (PMID 41210656, 2026). "Type 2 diabetes advances faster when islet amyloid polypeptide (IAPP) builds up in the body because it damages beta cells and makes insulin resistance worse." (PMID 40225541, 2025). "More than 90% of patients with type II diabetes have amyloid deposits of IAPP in their pancreas, as determined by post-mortem studies." (PMID 40765848, 2025). "The accumulation of misfolded islet amyloid polypeptide (IAPP) in pancreatic β‐cells, which reduces its normal secretion function, is a hallmark of type II diabetes." (PMID 40599234, 2025). "The aggregation of the islet amyloid polypeptide (IAPP) plays an important role in the pathology of type 2 diabetes (T2D)." (PMID 41395543, 2025). "Experiments have shown that individuals with type 2 diabetes and Alzheimer’s often exhibit co-localized deposits of IAPP and amyloid-β (Aβ), providing strong evidence of cross-seeding between these amyloid proteins." (PMID 41409210, 2025). "In the next section, we review what is currently known about IAPP and its critical role in pancreatic β-cell destruction and type II diabetes." (PMID 40765848, 2025). "In type 2 diabetes, IAPP has a strong tendency to pathologically aggregate into highly stable, β-sheet-rich amyloid fibrils within the islets of Langerhans, a process observed in over 90% of patients with the disease." (PMID 41409210, 2025).
type 2 diabetes (continued). "Human IAPP was initially discovered in amyloid isolated from pancreatic tumors and islets from patients with type 2 diabetes, indicating its amyloidogenic nature." (PMID 40046847, 2025). "Interestingly, type II diabetes caused by aberrant LLPS of IAPP may be connected to PD." (PMID 40599234, 2025). "The objectives of this study were to elucidate potential differences of IAPP oligomerisation levels in plasma between healthy individuals and people with type 2 diabetes." (PMID 39174611, 2024). "These amyloid deposits, primarily composed of the 37-residue islet amyloid polypeptide (IAPP), are a characteristic feature found in more than 90% of patients with type 2 diabetes." (PMID 39081432, 2024). "AD and type 2 diabetes are considered protein misfolding disorders associated with the accumulation of protein aggregates, namely Aβ and tau in the brain during AD and IAPP in pancreatic islets in type 2 diabetes." (PMID 39770025, 2024). "The deposition of IAPP is considered to be an important pathological feature of type 2 diabetes mellitus." (PMID 39595941, 2024). "One of the hallmarks of type 2 diabetes is the progressive accumulation and aggregation of human islet amyloid polypeptide (hIAPP), a small 37 amino acid peptide hormone secreted by the pancreas." (PMID 39615682, 2024). "For example, type II diabetes is related to the aggregation of islet amyloid polypeptide (IAPP), which leads to a decline in pancreatic β-cell function and mass." (PMID 38440398, 2024). "Taken together we have shown for the first time that the sFIDA technology works in blood plasma from people with type 2 diabetes to determine IAPP oligomer concentrations down to the fM range." (PMID 39174611, 2024). "Although this cannot prove that IAPP oligomerisation is the driving factor of type 2 diabetes development and progression, one would expect that the IAPP oligomerisation level is increasing with disease duration." (PMID 39174611, 2024). "Patients with type 2 diabetes mellitus are prone to develop amylin islet amyloid polypeptide (AIAPP amyloid) plaques in the pancreas due to its abnormally elevated production in pancreatic beta cells." (PMID 39081432, 2024). "The islet amyloid polypeptide (IAPP) plays a role in glucose homeostasis but aggregates to form islet amyloid in type 2 diabetes." (PMID 39770025, 2024). "Pancreas-derived islet amyloid polypeptide (IAPP) aggregates and deposits in the pancreas and periphery of Type 2 Diabetes (T2D) patients, contributing to diabetic complications." (PMID 39062913, 2024). "The aim of the present study was to investigate IAPP oligomerisation levels in human plasma samples of healthy controls and of people with type 2 diabetes." (PMID 39174611, 2024). "The study included alpha-synuclein, a human protein that is involved in Parkinson’s disease, and human islet amyloid polypeptide (hIAPP), which is involved in type 2 diabetes." (PMID 38097650, 2023). "In type 2 diabetes, human islet amyloid polypeptide (hIAPP) aggregates to form higher structure oligomers and fibrils that are toxic to beta cells and induce islet inflammation." (PMID 36634699, 2023). "Pancreas-derived islet amyloid polypeptide (IAPP) crosses the blood–brain barrier and co-deposits with amyloid beta (Aβ) in brains of type 2 diabetes (T2D) and Alzheimer’s disease (AD) patients." (PMID 36835187, 2023). "When IAPP increases in type 2 diabetes patients, IAPP can form a seed in the brain and provide as a nucleation core of Aβ plaque formation." (PMID 36834911, 2023). "Islet amyloid polypeptide (IAPP) accelerates the pathogenesis of type 2 diabetes by exacerbating β cell degeneration and ultimately compromising insulin secretion." (PMID 37601108, 2023). "In 90% of type 2 diabetes patients, plaques containing IAPP as the main component are observed in the pancreas." (PMID 36834911, 2023).
type 2 diabetes (continued). "In Parkinson’s disease, alpha-synuclein (aSyn) forms insoluble Lewy bodies and Lewy neurites in brain neurons, and in type 2 diabetes, islet amyloid polypeptide (IAPP) comprises the amyloid in the islets of Langerhans." (PMID 36793785, 2023). "Expression of a human IAPP hexamer (6xIAPP), designed to accelerate amyloid formation, accelerated type 2 diabetes development in mice." (PMID 37635876, 2023). "Antibody treatment in male rats and mice transgenic for human IAPP, and human islet-engrafted mouse models of type 2 diabetes triggers clearance of IAPP oligomers resulting in beta cell protection and improved glucose control." (PMID 37813862, 2023). "Further, it was also discovered that islet amyloid polypeptide (IAPP) aggregates to fibrillar structures leading to type II diabetes." (PMID 37511898, 2023). "Key mediators of the injury responses in islets transgenic for human IAPP or those from individuals with type 2 diabetes include STAT3, NF-κB, ESR1 and CTNNB1 by transcription factor analysis and COL3A1, NID1 and ZNF800 by gene regulatory network analysis." (PMID 34554282, 2022). "For example, the accumulation of α-synuclein contributes to the aggregation of islet amyloid polypeptide (IAPP), which has been linked to type 2 diabetes." (PMID 35631338, 2022). "Beta cell overexpression of soluble rodent or oligomer-prone human IAPP induced changes in islet transcriptome present in prediabetes and type 2 diabetes, including decreased expression of genes that confer beta cell identity." (PMID 34554282, 2022). "Type 2 diabetes is characterised by islet amyloid and toxic oligomers of islet amyloid polypeptide (IAPP)." (PMID 34554282, 2022). "The propensity of IAPP to form toxic oligomers defines the relative vulnerability of a species to develop type 2 diabetes." (PMID 34554282, 2022). "The pathogenesis of type 2 diabetes (T2D) is highly related to the abnormal self-assembly of the human islet amyloid polypeptide (hIAPP) into amyloid aggregates." (PMID 36142176, 2022). "The islet amyloid polypeptide (IAPP) is the main constituent of the amyloid fibrils found in the pancreas of type 2 diabetes patients." (PMID 35372496, 2022). "The system of interest was made of two amyloids, amyloid-β (Aβ) and islet amyloid polypeptide (IAPP), which are involved in the pathology of Alzheimer’s disease and type 2 diabetes mellitus." (PMID 36142260, 2022). "The study shows a high expression of Bri2 in human pancreatic islets and β-cells, as well as co-localization of Bri2 with IAPP both intracellularly and in the islet amyloid deposits from type 2 diabetes patients." (PMID 35327638, 2022). "Islet amyloid polypeptide (IAPP), or amylin, is a highly amyloidogenic, 37-residue polypeptide that has been strongly linked to the exacerbation of type 2 diabetes (T2D) prognosis." (PMID 35216095, 2022). "Beta cell injury mediated by IAPP is a plausible mechanism to contribute to islet inflammation and dedifferentiation in type 2 diabetes." (PMID 34554282, 2022). "Strategies to suppress IAPP expression warrant further investigation due to the mounting evidence to suggest its role in type 2 diabetes pathogenesis." (PMID 34554282, 2022). "This has been consistently observed in many protein systems including Aβ and tau in AD, αSyn in PD and human islet amyloid polypeptide (IAPP) in type II diabetes." (PMID 33791300, 2021). "UCHL1 relieves the apoptotic burden induced by the accumulation of intracellular toxic oligomers of islet amyloid polypeptide (IAPP) in pancreatic beta (β) cells, resulting in the suppression of type 2 diabetes." (PMID 33919439, 2021). "One of the indispensable characteristics of type 2 diabetes is the deposition of amyloid fibrils of islet amyloid polypeptide (IAPP) in the islets of Langerhans." (PMID 33920986, 2021).
type 2 diabetes (continued). "IAPP aggregates are identified for a majority (90%) of patients with type 2 diabetes and the true prevalence is likely to be even higher due to difficulties in identifying these aggregates in the pancreas." (PMID 34790701, 2021). "A similar observation was reported in human amyloid spherulites composed of islet amyloid polypeptide in the pancreatic tissue of type 2 diabetes mellitus." (PMID 33545172, 2021). "Human islet amyloid polypeptide (hIAPP) is an intrinsically disordered protein and plays a significant role in the progression of type 2 diabetes." (PMID 32117877, 2020). "One for all: A high‐affinity amyloid‐suppressing interaction between the human antimicrobial and immunomodulatory polypeptide cathelicidin LL‐37 and the key type 2 diabetes (T2D) amyloid polypeptide IAPP was identified." (PMID 31999880, 2020). "Aggregates of IAPP are present in the extracellular space of the islet of Langerhans in patients suffering from type II diabetes." (PMID 31936201, 2020). "Islet Amyloid Polypeptide (IAPP) accumulation is long recognized as a phenomenon occurring in human type 2 diabetes." (PMID 32477265, 2020). "For instance, intracellular aggregates of the islet amyloid polypeptide (IAPP) have been found to clog the ER translocon and to display prion-like properties, ultimately leading to β-cell failure and potentially to type 2 diabetes." (PMID 31963687, 2020). "Type II diabetes is characterized by the amyloid accumulation of the peptide hormone islet amyloid polypeptide (IAPP), while AD and PD are characterized by the accumulation of the amyloid beta (Aβ) and alpha synuclein (α-syn) peptides, respectively." (PMID 32372895, 2020). "The aggregation of human islet amyloid polypeptide (hIAPP) plays a major role in the pathogenesis of type 2 diabetes mellitus (T2DM), and numerous strategies for controlling hIAPP aggregation have been investigated so far." (PMID 33158138, 2020). "Misfolding and aggregation of the human islet amyloid polypeptide (hIAPP) are believed to play key roles in the pathophysiology of type-II diabetes." (PMID 36133854, 2020). "The accumulation of human islet amyloid polypeptide (hIAPP) in pancreatic islets under induction by a high-fat diet plays a critical role in the development of type-2 diabetes mellitus (T2DM)." (PMID 31507407, 2019). "The islet in type 2 diabetes (T2D) is characterized by amyloid deposits derived from islet amyloid polypeptide (IAPP), a protein co-expressed with insulin by β-cells." (PMID 31213603, 2019). "Various amyloid proteins are involved in metabolic diseases, such as β2-microglobulin in hereditary visceral amyloidosis, calcitonin in carcinoma of the thyroid, and islet amyloid polypeptide (IAPP) in type 2 diabetes." (PMID 30231587, 2018). "Human islet amyloid polypeptide (hIAPP), or amylin, has the tendency to aggregate into insoluble amyloid fibrils, a typical feature of islets from type 2 diabetes individuals." (PMID 29705815, 2018). "We identified many proteins and pathways whose expressions are affected by IAPP and which are therefore likely to be involved in the pathogenesis of type 2 diabetes." (PMID 30419808, 2018). "Amyloid formation in the pancreatic islets due to aggregation of human islet amyloid polypeptide (hIAPP) contributes to reduced β-cell mass and function in type 2 diabetes (T2D) and islet transplantation." (PMID 29474443, 2018). "The oligomerization and fibrillation of human islet amyloid polypeptide (hIAPP) play a central role in the pathogenesis of type 2 diabetes." (PMID 29535385, 2018). "Islet amyloid polypeptide (IAPP) or amylin deposits can be found in the islets of type 2 diabetes patients." (PMID 30419808, 2018). "Winter and co-workers have shown that resveratrol inhibits islet amyloid polypeptide (IAPP) aggregation, a mechanism involved in the pathogenesis of type-II diabetes mellitus." (PMID 30018739, 2018).